B2M (beta-2-microglobulin)
Diseases named in the same sentence as B2M in open-access papers (continued):
Sharing a sentence is not in itself a finding about the gene and the disease.
amyloidosis (continued). "The persistence of high concentrations of beta-2-microglobulin (β2M) in the blood of patients with acute renal failure leads to the development of the dialysis-related amyloidosis." (PMID 30223436, 2018). "A particular and rare form of amyloidosis is the dialysis related amyloidosis, formed by the wild type deposit of Beta 2-microglobulin, a complication of long-term renal replacement therapy." (PMID 30393640, 2018). "One of the major problems in such patients undergoing long-term hemodialysis is beta-2 microglobulin (β2M) amyloidosis." (PMID 29268797, 2017). "Carpal tunnel surgery suggested the presence of clinically evident beta-2 microglobulin related amyloidosis for at least 15 years." (PMID 28874122, 2017). "Chronic renal failure can cause several complications related to the process of dialysis as amyloidosis (dialysis related amyloidosis DRA) in which there is abnormal production of beta 2 microglobulin." (PMID 26113889, 2014). "By reducing the beta-2 microglobulin concentrations observed during hemodiafiltration, the incidence of amyloidosis can be reduced by approximately 50%." (PMID 23547981, 2013). "Histological alterations of the skin in uremic patients include severe microangiopathy and pericollogenous deposition of amyloid, identified as beta 2-microglobulin amyloidosis." (PMID 17760994, 2007). "Serum B2M is regarded as a biomarker for the severity of infections, amyloidosis, renal injury, lymphoproliferative diseases, and aging-related disorders, while the B2M on the cell membrane surface non-covalently binds to the heavy chain of MHC-I molecule to execute diverse immune functions." (PMID 40191187, 2025). "Moreover, B2M is involved in a condition called dialysis-related amyloidosis, where it forms amyloid fibrils that can lead to complications in patients undergoing long-term dialysis." (PMID 38474110, 2024). "Another justification is that B2M acts as a pro-senescence factor, which may partially activate amyloidosis, hence the high levels of B2M in stage 1." (PMID 37005674, 2023). "In addition, in patients with end-stage renal failure, elevated level of B2M is a source of amyloidosis, therefore cell therapy with ablated B2M would be highly desired in such situations as well." (PMID 33661977, 2021). "However, todate, a relationship between falls and elevated beta-2 microglobulin ordialysis-associated amyloidosis levels had not been described, at least not in thestudies we found." (PMID 34816874, 2021). "Indeed, B2M is one of the most extensively studied middle molecule uremic toxins in CKD patients (and especially in dialysis patients, where B2M is the major protein component in dialysis-related amyloidosis)." (PMID 24217396, 2013).
breast carcinoma (35 papers, 1990 to 2025). "The prevalence of B2M loss in primary tumors ranged between 0% (esophageal cancer) and 43% (breast cancer) and between 14% (renal cancer) and 56% loss (breast cancer) in metastatic disease." (PMID 38455061, 2024). "Previous studies have also linked B2M mutations to increased levels of local immune cytolytic activity in uterine, stomach, colorectal and breast cancer." (PMID 31345234, 2019). "Including Nigerian samples along with TCGA allowed us to identify PLK2, KDM6A, and B2M as novel significantly mutated genes in breast cancer, with the former two enriched in the HER2 + subtype." (PMID 30327465, 2018). "PLK2, KDM6A, and B2M are also identified as previously unreported significantly mutated genes in breast cancer." (PMID 30327465, 2018). "However, GAPDH and TBP in hepatic cancer cell lines and ACTB and B2M in breast cancer cell lines have M values > 1, which causes us to consider them as unstable reference genes." (PMID 34752497, 2021). "We further unbiasedly analyzed the USP22 and B2M transcripts in breast cancer cell lines listed in Cancer Cell Line Encyclopedia (CCLE)." (PMID 41252204, 2025). "Previous studies have successfully utilized CRISPR/Cas9 technology to establish knockout models of B2M, JAK1, and LMP2 in the mouse EMT6 breast cancer cell line, as well as B2M knockout clone model in the mouse MC38 colon cancer cell line." (PMID 40191187, 2025). "Increased variation in HLA and B2M expression was observed in both breast cancer subtypes compared to normal adjacent tissues." (PMID 38281021, 2024). "We investigated the differential expression of HLA and B2M across two different subtypes of breast cancer including the ER + /HER2- and TNBC primary tumors from the publicly available dataset." (PMID 38281021, 2024). "Impaired antigen presentation as result of loss of B2M (encoding beta-2-microglobulin) and HLA-A deletion is associated with an immune-desert TME in breast cancer." (PMID 37222922, 2023). "The B2M gene was expressed higher in hepatic carcinoma and breast cancer while being more stably expressed in liver cancer, and it has not yet been reported as per the knowledge we have." (PMID 35770000, 2022). "According to the ΔCt method, TRA2B, RHOA, and THRAP3 were the most stably expressed genes, while DNAJC8, GAPDH, and B2M were the least stable genes in the breast cancer tissue group, which was consistent with the analysis according to NormFinder." (PMID 34895237, 2021). "In squamous cell carcinoma and breast cancer, tissue B2M levels have also been shown to be independent prognostic factors predictive of overall survival." (PMID 33960680, 2021). "In an investigation of canine articular connective tissue, GAPDH and B2M were found to be highly stable, while in canine mammary tumors, GAPDH was less stable." (PMID 29178874, 2017). "On the other hand, the down-modulated genes codify for proteins involved in cell migration and invasion (SNAI2 and B2M) as well as for proteins (TFPI2) with a tumor suppressor role in breast cancer." (PMID 24962430, 2014). "Additionally, upregulated B2M is also associated with a poorer prognosis, and NECTIN2 is a potential target of antibody therapy for breast cancer." (PMID 38783355, 2024). "Because the upregulation of B2M in the ICEC regions in ER+ breast cancers was among the most significant changes after ET, we sought to investigate the cancer cell–intrinsic effects of ER perturbation on MHC-I expression in ER+ breast cancer cell lines (MCF7, T47D, CAMA1, and ZR75.1)." (PMID 37450351, 2023). "We also found that B2M was more stable in hepatobiliary and breast cancers than the other genes." (PMID 35770000, 2022). "In addition, GUSB, TUBA1A, RPL13A, and B2M, which previous studies suggested being stable RGs in breast cancer research, and two classical RGs, ACTB and GAPDH, were also considered." (PMID 34895237, 2021).
breast carcinoma (continued). "In addition, THRAP3, TARDBP, and YY1 were the most stably expressed genes in the breast cancer cell lines, while B2M, TUBA1A, and ACTB were the least stably expressed genes." (PMID 34895237, 2021). "B2M expression demonstrated a significant difference in the breast cancer molecular subtypes, and may be related to apoptosis regulation in breast cancer." (PMID 27526934, 2016). "A series of ten colorectal and ten breast carcinomas, and their respective lymph node metastases, were examined immunohistologically using monoclonal antibodies (mAb) against both monomorphic and A2 polymorphic determinants, and beta-2-microglobulin (beta 2m)." (PMID 1718386, 1991). "B2M shows its highest regulation in myeloid cells across all subtypes, with the only exception of HER2+ breast cancers, where myeloid cells were also upregulated but slightly outcompeted by T-cells (ΔB2M,myel." (PMID 38940181, 2024). "The tumor-specific marker genes (i.e. EPCAM, KRT8, EPCAM, B2M, FCA1 and KRT19) were also highly expressed in the tumor regions of prostate, colorectal, liver cancer, pancreas and breast cancer." (PMID 36243975, 2023). "For example, B2M, CALML5, and HSPD1 are largely breast cancer–specific markers, but even these differ in their expression across the different three breast cancer PDXs." (PMID 36470535, 2023). "Our results overally indicated that GAPDH, YWHAZ, and UBC were the most stable reference genes in breast cancer cell lines, including MCF7, SKBR3 and MDA-MB231, and B2M and ACTB were the least stable ones." (PMID 34752497, 2021). "In breast cancer cell lines, exactly the same ranking order as the geNorm algorithm was reported in which UBC and B2M were the most and the least stable genes, respectively." (PMID 34752497, 2021). "In the breast cancer tissue group DNAJC8, RPL13A, and TARDBP were the most stably expressed genes, while ACTB, B2M, and GAPDH were the least stably expressed genes." (PMID 34895237, 2021). "In the breast cancer cell line group, THRAP3, RHOA, and QRICH1 were the three most stably expressed genes, while B2M, ACTB, and TUBA1A were the least stably expressed genes." (PMID 34895237, 2021). "In the breast cancer tissue group, the three most stably expressed genes (with the lowest M values) were SF1, THRAP3, and TARDBP, while GAPDH, DNAJC8, and B2M were the least stably expressed genes." (PMID 34895237, 2021). "In the breast cancer cell group THRAP3, RHOA, and QRICH1 were the top three stably expressed genes, while B2M, TUBA1A, and ACTB were the least stably expressed genes." (PMID 34895237, 2021). "In the breast cancer cell group, THRAP3, DNAJC8, and RPL13A were the three most stably expressed genes, while TUBA1A, B2M, and ACTB were the least stably expressed genes." (PMID 34895237, 2021). "For all breast cancer tissue and cell line samples, THRAP3, RHOA, QRICH1 were the most stably expressed genes, and TUBA1A, B2M, ACTB were the least stably expressed RGs." (PMID 34895237, 2021). "In the breast cancer tissue group, TRA2B, RHOA, and THRAP3 were the most stable genes, and DNAJC8, GAPDH, and B2M were the most unstable genes." (PMID 34895237, 2021). "The impact of RelA silencing on B2M was statistically significant, but the absolute difference was limited, which is consistent with the notion that other transcription factors, such as IRF1, facilitate the upregulation of B2M in ER+ breast cancer cells as in other cell types." (PMID 37450351, 2023). "Statistical analysis showed that B2M, which forms the small light chain subunit of the MHC Class I molecules and plays a crucial role in antigen presentation, was downregulated in ER + breast cancer, but was not significantly different in TNBC subtype compared to matched normal samples." (PMID 38281021, 2024).
colorectal cancer (32 papers, 2010 to 2025). A primary or metastatic malignant neoplasm that affects the colon or rectum. "B2M gene alterations have been reported to associate with defective HLA-1 expression in colorectal carcinoma." (PMID 36606194, 2022). "The association of B2M gene alteration with defective HLA-1 expression was reported in several cancers, including colorectal carcinoma and lymphomas." (PMID 36606194, 2022). "An association of B2M mutations with improved survival under adjuvant therapy had previously been reported for MSI colorectal cancer patients." (PMID 34168989, 2021). "Previous studies have demonstrated that B2M loss limits the metastatic potential in MSI colorectal cancer and other tumor types, such as uveal melanoma." (PMID 34168989, 2021). "Additionally, we observed that the low-expression group exhibited a high mutational load, with FBXW7, SOX9, AMER1, SMAD4, ARID1A, and B2M being the most frequently mutated genes in colorectal cancer." (PMID 40170839, 2025). "B2M mutations are found in 3.4% of patients with colorectal cancer." (PMID 34385592, 2022). "Notably, B2M mutations were highly enriched in tumors with microsatellite instability, a phenomenon that has been previously observed in the context of colorectal cancer and is now confirmed for other tumor types with high MSI." (PMID 31345234, 2019). "B2M mutations occur frequently in mismatch repair‐deficient colorectal cancer (dMMR CRC), with limited data suggesting they may protect against recurrence." (PMID 31062389, 2019). "Nevertheless, some studies have reported that 85% of B2M mutant colorectal cancer patients can benefit from ICIs, manifested as disease stability or partial remission." (PMID 40191187, 2025). "Similar to B2M, mutations in the ‘phosphatase-and-tensin-homologue’ PTEN tumour suppressor gene are more frequently found in MSI-H colorectal cancer, and specifically in locally advanced or metastatic cancers." (PMID 40702107, 2025). "In colorectal cancer (CRC), B2M mutation was proposed to reshape the microsatellite-unstable (MSU) CRC for resistance of ICB treatment." (PMID 33658560, 2021). "In our cohort, only 4 patients had colorectal cancer with KRAS/NRAS mutations, three of them (all B2M-wt) received ICB therapy and showed PR as best response." (PMID 34168989, 2021). "In colorectal cancer and squamous cell carcinoma, B2M expression was upregulated, which is consistent with findings from previous studies." (PMID 33960680, 2021). "On the contrary, several studies have indicated that B2M is upregulated in both colorectal cancer and squamous cell carcinoma to contribute to tumor progression." (PMID 33960680, 2021). "This study has determined B2M mutation status and its influence on recurrence in QUASAR, the largest randomised trial of adjuvant chemotherapy in colorectal cancer." (PMID 31062389, 2019). "Methylation of the B2M gene promoter was observed to interrelate with transcriptional inactivation and down-regulation of B2M expression in colorectal cancer featuring microsatellite instability (MSI), which was up-regulated using the DNA methyltransferase inhibitor, DNMTi." (PMID 40191187, 2025). "We selected three candidate colorectal cancer biomarkers (B2M, TIMP-1, and CLU)." (PMID 36792801, 2023). "B2M aberrations contribute ICB resistance in patients with colorectal cancer." (PMID 34385592, 2022). "In MSI colorectal cancers, loss of HLA class I expression owing to mutations in B2M was considered to be a negative predictor for ICI therapy." (PMID 36611830, 2022). "Stomach, uterine and colorectal cancers have documented high rates of microsatellite instability (MSI), thus we evaluated whether B2M and HLA mutations were biased to occur in high MSI tumors." (PMID 31345234, 2019). "However, B2M frameshift mutations, also leading to immune escape via loss of HLA class 1 expression, frequently occur in MSI colorectal cancer and are a rare phenomenon in MSI endometrial cancer." (PMID 27213585, 2016).
colorectal cancer (continued). "In colorectal cancer, miR-148a-3p is eminently capable of repressing the expression of calnexin (CANX) and B2M/MHC-I, thereby decidedly restricting the anti-cancer efficacy of CTLs." (PMID 40191187, 2025). "Thus, while it is evident that JAK1, JAK2, and B2M mutations can contribute to immune resistance in multiple types of cancer, the loss of IFNγ signaling gene expression may be the predominant source of ICB resistance in colorectal cancer." (PMID 34385592, 2022).
lymphoma (31 papers, 1993 to 2025). A malignant (clonal) proliferation of B- lymphocytes or T- lymphocytes which involves the lymph nodes, bone marrow and/or extranodal sites. "The raised beta-2 microglobulin levels, along with the significant family history of lymphoma, increased the pre-diagnostic probability of lymphoma." (PMID 41018366, 2025). "In pSS patients, serum B2M has been associated with extra-glandular systemic manifestations, including the development of lymphoma." (PMID 39795957, 2024). "The DLBCL associated (epi-)genetic alterations in CD58 and B2M result in loss-of-function, allowing lymphoma cells to escape immune responses." (PMID 33260693, 2020). "B2M mutations were associated with a significantly reduced CD8+ T cell infiltrate in transformed lymphoma biopsies." (PMID 27959929, 2016). "Moreover, lymphomas exhibit abnormally high B2M mutation rates compared with solid cancer, and about half of the patients carrying B2M aberrations show bi-allelic inactivating alterations." (PMID 36959853, 2023). "An advanced allogeneic CD19‐CAR iNKT product co‐expressing IL‐15 and shRNAs against B2M/CD74 (to reduce HLA‐I/II expression) demonstrated efficacy in R/R non‐hodgkin lymphoma and acute lymphoblastic leukemia." (PMID 41292193, 2025). "Laboratory findings included elevated beta-2-microglobulin and positive antinuclear antibodies, raising suspicion of lymphoma or other malignancies." (PMID 39834986, 2024). "We modified the RMA lymphoma line by means of CRISPR-Cas9–mediated genome editing to knock out B2m expression." (PMID 39196934, 2024). "In patients with pSS, the serum B2M is correlated with disease activity and extra-glandular systemic involvement, representing a prognostic factor for lymphoma development." (PMID 39795957, 2024). "The serum B2M levels in a patient with lymphoma, similar to the serum LDH levels, have been widely accepted as directly related to tumor burden." (PMID 32219067, 2020). "Correlation between tumor burden and serum B2M has been previously suggested because serum B2M is frequently elevated in patients with lymphoma." (PMID 29228708, 2017). "Loss of expression of B2M, and gain of expression of PRDX1 and PPIA was confirmed in the cell lines and primary lymphoma tissue." (PMID 26752561, 2016). "A high serum B2m level is an independent adverse prognostic factor in malignant lymphoma, which is also related to the tumor burden." (PMID 24454777, 2014). "Moreover, serum B2M has been recognized as a biomarker for a variety of diseases, such as lymphoma, coronary artery, inflammatory, central nervous system and autoimmune diseases." (PMID 40191187, 2025). "With ~20% of DLBCL harboring PD-L1 positive lymphomas, the presence of B2M alterations may be important in ICI directed against the programmed death 1 (PD-1)/PD ligand 1 (PD-L1) interaction in R/R DLBCL." (PMID 33260693, 2020). "beta-2 microglobulin levels were measured in stored serum taken at presentation from 262 patients treated with combination chemotherapy for Kiel classification high-grade lymphoma at a single centre over a 15 year period." (PMID 8471438, 1993). "Finally, mutations in TNFRSF14 (15% in progression cases of GCB COO) and B2M (8% in all progression cases) may promote lymphomagenesis by affecting the immune system response to lymphoma." (PMID 39392347, 2024). "TCR/B2M KO reduces GvHD and enhances the efficacy of universal CAR-T cells in patients with relapsed/refractory lymphoma." (PMID 40191187, 2025). "When we correlated the RCN compositions in DLBCLs with the expression of HLA and B2M, we found that B2M and HLA-ABC–positive lymphomas consisted of a smaller proportion of the B cell rich with immune cells RCN1 (adj." (PMID 40772779, 2025). "Our data indicated that proliferating lymphoma cells down-expressed GAPDH and B2M, but after GM treatment, useful for inducing cell death, the gene expression increased." (PMID 25622250, 2015).